TARDBP (TAR DNA binding protein)
Description:
RNA-binding protein that is involved in various steps of RNA biogenesis and processing. Preferentially binds, via its two RNA recognition motifs RRM1 and RRM2, to GU-repeats on RNA molecules predominantly localized within long introns and in the 3'UTR of mRNAs. In turn, regulates the splicing of many non-coding and protein-coding RNAs including proteins involved in neuronal survival, as well as mRNAs that encode proteins relevant for neurodegenerative diseases. Plays a role in maintaining mitochondrial homeostasis by regulating the processing of mitochondrial transcripts. Also regulates mRNA stability by recruiting CNOT7/CAF1 deadenylase on mRNA 3'UTR leading to poly(A) tail deadenylation and thus shortening. In response to oxidative insult, associates with stalled ribosomes localized to stress granules (SGs) and contributes to cell survival. Also participates in the normal skeletal muscle formation and regeneration, forming cytoplasmic myo-granules and binding mRNAs that encode sarcomeric proteins. Plays a role in the maintenance of the circadian clock periodicity via stabilization of the CRY1 and CRY2 proteins in a FBXL3-dependent manner. Negatively regulates the expression of CDK6. Regulates the expression of HDAC6, ATG7 and VCP in a PPIA/CYPA-dependent manner.
Synonyms: TDP-43; ALS10
Tractability: PROTAC: UniProt records ubiquitination sites on it; ubiquitination databases record sites on it; its protein half-life has been measured; a small molecule that binds it is known.
Gene: Protein-coding gene on chromosome 1 (11,012,344 to 11,030,528, forward strand). Ensembl gene ENSG00000120948.
Subcellular location: Nucleus; Cytoplasm; Cytoplasm, Stress granule; Mitochondrion
Subcellular location (Human Protein Atlas): Nucleoplasm
Gene Ontology:
Molecular function: DNA binding; double-stranded DNA binding; identical protein binding; lipid binding; molecular condensate scaffold activity; mRNA 3'-UTR binding; protein binding; RNA binding; nucleic acid binding; pre-mRNA intronic binding; RNA polymerase II cis-regulatory region sequence-specific DNA binding
Biological process: 3'-UTR-mediated mRNA destabilization; 3'-UTR-mediated mRNA stabilization; amyloid fibril formation; host-mediated suppression of viral transcription; negative regulation of gene expression; negative regulation of protein phosphorylation; nuclear inner membrane organization; regulation of apoptotic process; regulation of cell cycle; regulation of protein stability; RNA splicing; regulation of gene expression; positive regulation of insulin secretion; positive regulation of protein import into nucleus; regulation of circadian rhythm; response to endoplasmic reticulum stress
Cellular component: cytoplasm; mitochondrion; nucleoplasm; nucleus; chromatin; cytoplasmic stress granule; interchromatin granule; nuclear speck; perichromatin fibrils
Genetic constraint (gnomAD): Loss-of-function variants: 4 observed, 39.89 expected, observed/expected ratio (o/e) 0.1, 90% interval 0.048 to 0.23. The upper end of that interval is the gene's LOEUF score, 0.23, which puts it in group 1 of 6, group 1 being the genes least tolerant of losing a copy. Missense variants: 202 observed, 540.64 expected, observed/expected ratio (o/e) 0.37, 90% interval 0.33 to 0.42. Synonymous variants: 184 observed, 190.32 expected, observed/expected ratio (o/e) 0.97, 90% interval 0.86 to 1.09.
Gene-disease validity (ClinGen):
ClinGen rates the evidence that TARDBP causes each of these diseases.
amyotrophic lateral sclerosis type 10 (autosomal dominant): Definitive.
Homologues: Orthologues: chimpanzee TARDBP (100% identical), macaque TARDBP (99% identical), guinea pig TARDBP (98% identical), pig TARDBP (98% identical), mouse Tardbp (96% identical), rat Tardbp (96% identical), tropical clawed frog tardbp (85% identical), rabbit TARDBP (77% identical), zebrafish tardbpb (75% identical), zebrafish tardbpa (57% identical), Drosophila melanogaster TBPH (51% identical), Drosophila melanogaster cocoon (36% identical), and 1 more. Paralogues in human: PABPC1 (21% identical), PABPC1L (21% identical), PABPC4 (20% identical), PABPC3 (20% identical), RBM45 (19% identical), PABPC4L (15% identical), SYNCRIP (15% identical), RBMS3 (14% identical), HNRNPR (14% identical), RBMS1 (14% identical), PABPC5 (13% identical), RBMS2 (13% identical), and 12 more.
Diseases named in the same sentence as TARDBP in open-access papers:
TARDBP is named in the same sentence as 324 diseases in open-access papers, as found by Europe PMC text mining. Sharing a sentence is not in itself a finding about the gene and the disease. The quoted sentences say what the papers report.
amyotrophic lateral sclerosis (1,478 papers, 2008 to 2026). Amyotrophic lateral sclerosis (ALS) is a neurodegenerative disease characterized by progressive muscular paralysis reflecting degeneration of motor neurons in the primary motor cortex, corticospinal tracts, brainstem and spinal cord. "TAR DNA-binding protein 43 (TDP-43) aggregation is a hallmark of several neurodegenerative diseases, including amyotrophic lateral sclerosis and frontotemporal dementia." (PMID 41727032, 2026). "TAR DNA-binding protein 43 (TDP-43) dysfunction is a hallmark of several neurodegenerative diseases, including frontotemporal dementia, amyotrophic lateral sclerosis, and Alzheimer’s disease." (PMID 41490046, 2026). "TAR DNA-binding protein 43 (TDP-43) is a major pathogenic RNA-binding protein associated with amyotrophic lateral sclerosis (ALS)." (PMID 42254864, 2026). "Mutations in RBPs contribute to multiple neurodegenerative disorders including mutated FMRP (fragile X mental retardation protein) in fragile X syndrome (FXS) and mutated TDP43 (TAR DNA-binding protein 43) in amyotrophic lateral sclerosis (ALS)." (PMID 39966655, 2025). "Analogously, CLU has been shown to interact with TAR DNA-Binding Protein 43 (TDP-43), which is associated with amyotrophic lateral sclerosis and frontotemporal degeneration." (PMID 40650133, 2025). "Mutations in the TARDBP gene, which encodes the TDP-43 protein, account for only 3–5% of familial cases of amyotrophic lateral sclerosis and less than 1% of cases that are apparently idiopathic." (PMID 40252666, 2025). "Mutations in FUS and TARDBP cause amyotrophic lateral sclerosis (ALS), but the precise mechanisms of selective motor neuron degeneration remain unresolved." (PMID 40389397, 2025). "In this fourth paper of a Series on Genetic Amyotrophic Lateral Sclerosis, we review the evidence on TARDBP mutations that cause ALS and frontotemporal dementia." (PMID 40252666, 2025). "Mutations in TARDBP have been associated with amyotrophic lateral sclerosis (ALS), frontotemporal dementia (FTD) with parkinsonism, and AD." (PMID 40332547, 2025). "The TDP-43 gene (TAR DNA-binding protein 43) has been implicated in both sporadic and familial forms of amyotrophic lateral sclerosis (ALS) and frontotemporal dementia (FTD)." (PMID 41181712, 2025). "While it does not directly trigger disease development, TMEM106B is linked to TAR DNA-binding protein (TDP-43) pathology and cognitive issues in amyotrophic lateral sclerosis (ALS)." (PMID 39872397, 2024). "The structure of TAR DNA-binding protein 43 (TDP-43), associated with amyotrophic lateral sclerosis and frontotemporal dementia, was studied through all-atom MD simulations at 100 and 300 mM NaCl to understand its phase separation behavior." (PMID 39432675, 2024). "Aggregation of the Tar DNA-binding protein of 43 kDa (TDP-43) is a pathological hallmark of amyotrophic lateral sclerosis and frontotemporal dementia and likely contributes to disease by loss of nuclear function." (PMID 37384248, 2023). "Mutations of the TARDBP gene are associated with neurodegenerative diseases, especially with amyotrophic lateral sclerosis; this gene encodes the TDP-43 protein, which is implicated in the apparition of this ND." (PMID 37445986, 2023). "Mutations in the 43 kDa transactive-response (TAR)-DNA-binding protein (TARDBP) are associated with 2–5% of familial Amyotrophic Lateral Sclerosis (ALS) cases." (PMID 38002982, 2023). "Abnormal aggregation of the TAR DNA-binding protein 43 kDa (TDP-43) is associated with multiple human diseases such as amyotrophic lateral sclerosis, frontotemporal lobar degeneration, and Alzheimer’s disease." (PMID 37853696, 2023). "The TARDBP gene mutation, A382T, has been associated with an increased susceptibility for motor neuron diseases such as amyotrophic lateral sclerosis." (PMID 37445986, 2023).
amyotrophic lateral sclerosis (continued). "For example, propagation of abnormally phosphorylated cytoplasmic inclusions of TAR-DNA-Binding protein (TDP-43) is proposed to underlie progression of amyotrophic lateral sclerosis (ALS) and frontotemporal dementia (FTD)." (PMID 36810738, 2023). "TAR DNA-binding protein 43, mostly referred to as TDP-43 (encoded by the TARDBP gene) is strongly linked to the pathogenesis of amyotrophic lateral sclerosis (ALS) and frontotemporal dementia (FTD)." (PMID 35185458, 2022). "Protein aggregation of TARDBP/TDP-43 is a hallmark of amyotrophic lateral sclerosis (ALS) and frontotemporal dementia (FTD) pathology which has specifically been described in motor neurons harboring TBK1 mutations." (PMID 40396014, 2022). "Aggregation, cellular mislocalization and loss of nuclear TDP-43 (TAR DNA binding protein) are hallmarks of amyotrophic lateral sclerosis (ALS), frontotemporal dementia (FTD) and limbic-predominant age-related TDP-43 encephalopathy (LATE)." (PMID 35495061, 2022). "Here, we show that TAR DNA–binding protein 43 (TDP-43), mutations in which constitute a major risk factor for amyotrophic lateral sclerosis, inhibits L1 retrotransposition in mouse embryonic stem cells (mESCs) and preimplantation embryos." (PMID 36417507, 2022). "TAR DNA-binding protein 43 (TDP-43) forms intraneuronal cytoplasmic inclusions associated with amyotrophic lateral sclerosis and ubiquitin-positive frontotemporal lobar degeneration." (PMID 35807552, 2022). "Here, we exploited the catRAPID algorithm to generate aptamers targeting TAR DNA-binding protein 43 (TDP-43), whose aggregation is associated with Amyotrophic Lateral Sclerosis." (PMID 35739092, 2022). "Recently, in a stable cell line that expresses mutated TAR DNA-binding protein-43 to mimic the pathology of amyotrophic lateral sclerosis, MG132 treatment promoted neurite extension." (PMID 33147870, 2020). "Many mutated proteins in neurodegenerative diseases are autophagy targets (e.g., mutated α-synuclein in Parkinson’s disease, mutated huntingtin in Huntington’s disease or mutants of TAR DNA-binding protein 43 (TDP-43) in amyotrophic lateral sclerosis)." (PMID 32245178, 2020). "Pathological forms of TAR DNA-binding protein 43 (TDP-43) are present in almost all cases of amyotrophic lateral sclerosis (ALS), and 20% of familial ALS cases are due to mutations in superoxide dismutase 1 (SOD1)." (PMID 32446203, 2020). "A limitation of current research is a significant bias towards models based on superoxide dismutase 1, with uncertainty about generalisability to amyotrophic lateral sclerosis with an underlying TAR DNA binding protein 43 proteinopathy." (PMID 32133457, 2019). "The cytoplasmic accumulation of the nuclear TAR DNA-binding protein 43 (TDP-43) is a pathologic hallmark in amyotrophic lateral sclerosis, frontotemporal lobar degeneration, and other neurological disorders." (PMID 30810811, 2019). "It has been shown that mutation in FUS and TARDBP are related to amyotrophic lateral sclerosis(ALS), a motor neuron disease by leading to neuronal cell death." (PMID 31017923, 2019). "TAR DNA-binding protein (TDP-43) is a nuclear protein that has been implicated in amyotrophic lateral sclerosis (ALS)." (PMID 29615863, 2018). "For example, in TDP-43 (TAR DNA-binding protein) single residue substitution mutation in the Gln/Asn-enriched LCR forms irreversible protein aggregates which are involved in amyotrophic lateral sclerosis and frontotemporal lobar dementia." (PMID 30397544, 2018). "Fragments of the TAR DNA-binding protein 43 (TDP43) are major components of intracellular aggregates associated with amyotrophic lateral sclerosis and frontotemporal dementia." (PMID 29987190, 2018). "In humans, tardbp mutation is causative in amyotrophic lateral sclerosis, and TARDBP aggregates in multiple neurodegenerative diseases." (PMID 28716093, 2017).
amyotrophic lateral sclerosis (continued). "Mutations in the TARDBP gene, encoding TDP-43, have been linked to familial forms of amyotrophic lateral sclerosis, thus arguing for a pathogenic role of TDP-43." (PMID 26507309, 2016). "Mutations in FUS/TLS, as well as in the RBP TAR DNA-binding protein 43 (TDP-43), were found to be causative of familial cases of amyotrophic lateral sclerosis (ALS), further implicating altered RNA metabolism as a central feature of these diseases." (PMID 24082883, 2013). "Mutations in the SOD1 and TARDBP genes have been commonly identified in Amyotrophic Lateral Sclerosis (ALS)." (PMID 21829392, 2011). "Progressive aggregation of TAR DNA-binding protein 43 (TDP-43) is a hallmark of numerous neurodegenerative diseases, including amyotrophic lateral sclerosis, frontotemporal dementia, Alzheimer's disease, and limbic predominant age-related TDP-43 encephalopathy (LATE)." (PMID 41609580, 2026). "Similarly, mutant huntingtin protein drives Huntington’s disease (HD), and TAR DNA-binding protein (TDP)-43 aggregates are implicated in Amyotrophic Lateral Sclerosis (ALS)." (PMID 40430519, 2025). "Cytoplasmic aggregates of the predominantly nuclear TAR DNA-binding protein 43 (TDP-43) are a pathological hallmark of amyotrophic lateral sclerosis (ALS) and frontotemporal dementia (FTD) cases caused by G4C2 hexanucleotide repeat expansions in C9orf72 (C9-ALS/FTD)." (PMID 40581653, 2025). "TAR DNA-binding protein 43 (TDP-43) proteinopathy is a central hallmark of amyotrophic lateral sclerosis (ALS) and frontotemporal dementia (FTD), yet current experimental models fail to reproduce the full pathological spectrum without external stress or TDP-43 overexpression." (PMID 41292965, 2025). "Additionally, TAR DNA-binding protein 43 (TDP-43), a major hallmark of amyotrophic lateral sclerosis, was detected in human post-mortem brains from patients with AD and DLB; phosphorylated TDP-43 was present in most AD cases and in a subset of DLB cases." (PMID 41465242, 2025). "Neuronal degeneration in the central nervous system (CNS) linked to TAR DNA-binding protein of 43kD (TDP-43) pathology is a prominent hallmark of several neurodegenerative diseases, including amyotrophic lateral sclerosis (ALS) and frontotemporal degeneration (FTD)." (PMID 38343852, 2024). "In addition, TARDBP was a risk factor for amyotrophic lateral sclerosis, frontotemporal dementia, and Alzheimer's disease, exacerbating cognitive impairment." (PMID 38836117, 2024). "Cytoplasmic inclusions of phosphorylated TAR DNA-binding protein-43 (TDP-43) are a pathological hallmark of several neurodegenerative disorders including amyotrophic lateral sclerosis (ALS), frontotemporal dementia (FTD) and limbic-predominant age-related TDP-43 encephalopathy (LATE)." (PMID 38175301, 2024). "Genetic alterations in RNA-binding proteins can lead to genetic diseases, including amyotrophic lateral sclerosis caused by fused-in-sarcoma (FUS)/TAR DNA binding protein-43 (TDP-43) mutations, and myelodysplastic syndromes caused by U2AF35/ splicing factor 3b subunit 1 (SF3B1) mutations." (PMID 37480049, 2023). "TARDBP gene mutations have long been linked with amyotrophic lateral sclerosis." (PMID 37445986, 2023). "Nuclear depletion and cytoplasmic aggregation of the TAR DNA-binding protein 43 (TDP-43) is a pathological hallmark of amyotrophic lateral sclerosis (ALS) and frontotemporal dementia (FTD) patients caused by a hexanucleotide repeat expansion mutation in the C9ORF72 gene (C9-ALS and C9-FTD)." (PMID 37466726, 2023). "Notably, cytoplasmic accumulation of TAR DNA binding protein 43 (TDP-43), a disease hallmark of amyotrophic lateral sclerosis (ALS), can trigger mtDNA release via the MPTP and VDAC1 oligomers to upregulate the NF-κB and cGAS-STING signaling." (PMID 37325622, 2023).
amyotrophic lateral sclerosis (continued). "Cytoplasmic mislocalization and aggregation of TAR DNA-binding protein-43 (TDP-43) is a hallmark of the amyotrophic lateral sclerosis and frontotemporal dementia (ALS/FTD) disease spectrum, causing both nuclear loss-of-function and cytoplasmic toxic gain-of-function phenotypes." (PMID 36482422, 2022). "Moreover, Hero proteins can prevent amyotrophic lateral sclerosis (ALS)-associated pathogenic protein aggregations of TAR DNA-binding protein of 43 kDa (TDP-43) in cultured motor neurons and in Drosophila models for neurodegenerative diseases." (PMID 35714106, 2022). "Stress granules (SGs) are hypothesized to facilitate TAR DNA-binding protein 43 (TDP-43) cytoplasmic mislocalization and aggregation, which may underly amyotrophic lateral sclerosis pathology." (PMID 32992901, 2020). "For example, mutations in the genes encoding the RBPs Fused in sarcoma (FUS) and TAR DNA-binding protein 43 (TDP-43) have been linked to the pathogenesis of amyotrophic lateral sclerosis, and the proteins were depleted from the nucleus and aggregated in the cytoplasm in affected neurons." (PMID 33193718, 2020). "Detergent-resistant, ubiquitinated and hyperphosphorylated Tar DNA binding protein 43 (TDP-43, encoded byTARDBP) neuronal cytoplasmic inclusions are the pathological hallmark in ∼95% of amyotrophic lateral sclerosis and ∼60% of frontotemporal lobar degeneration cases." (PMID 26936937, 2016). "Mutations in TARDBP cause some cases of TDP-43-proteinopathy in amyotrophic lateral sclerosis." (PMID 24466128, 2014). "Dysfunction of two structurally and functionally related proteins, FUS and TAR DNA-binding protein of 43 kDa (TDP-43), implicated in crucial steps of cellular RNA metabolism can cause amyotrophic lateral sclerosis (ALS) and certain other neurodegenerative diseases." (PMID 23867462, 2013). "TAR DNA‐binding protein 43 (TDP‐43) aggregation is a hallmark of several neurodegenerative diseases, including amyotrophic lateral sclerosis (ALS), PD, frontotemporal dementia (FTD), AD and limbic predominant age‐related TDP‐43 encephalopathy (LATE)." (PMID 41404649, 2026). "Ataxin 2 (ATXN2), an RBP that when mutated by polyglutamine (polyQ) expansion causes spinocerebellar ataxia type 2 (SCA2), was shown to bind to the amyotrophic lateral sclerosis (ALS)–linked Tar DNA-binding protein 43 (TDP-43)." (PMID 39955058, 2025). "In Parkinson’s Disease (PD), there is pathological increases in the phosphorylation of α-Synuclein (α-syn), while hyperphosphorylation of TAR DNA-binding protein 43 (TDP-43) is a hallmark of amyotrophic lateral sclerosis (ALS) neuropathology." (PMID 40045019, 2025). "TDP-43, an RNA-binding protein (RBP) encoded by the TARDBP gene, is crucial for understanding the pathogenesis of neurodegenerative diseases like amyotrophic lateral sclerosis (ALS) and frontotemporal lobar degeneration." (PMID 40778857, 2025). "Neuronal and glial cytoplasmic inclusions positive for TAR DNA-binding protein 43 (TDP-43) are the defining pathological hallmark of 97% of amyotrophic lateral sclerosis (ALS) and 50% of frontotemporal dementia (FTD)." (PMID 40826370, 2025). "TAR DNA-binding protein 43 (TDP-43) pathology is linked to the neurodegenerative disorders amyotrophic lateral sclerosis (ALS), frontotemporal dementia (FTD) and Huntington disease (HD)." (PMID 40426231, 2025). "Previous genetic analyses of some familial and sporadic amyotrophic lateral sclerosis (ALS) cases have identified over 50 missense mutations in the TARDBP gene." (PMID 39988698, 2025). "Among these four variants, PSEN1 p.R269H and TARDBP p.G287S had been previously reported as causes of AD and amyotrophic lateral sclerosis (ALS), respectively, while the remaining two variants in the APP and PSEN2 genes were novel." (PMID 40813364, 2025).